STC2 (stanniocalcin 2)
Diseases named in the same sentence as STC2 in open-access papers (continued):
Sharing a sentence is not in itself a finding about the gene and the disease.
placental disorders (1 paper, 2022). "In this study, the atomic cryo-EM structures of PAPP-A·proMBP and PAPP-A·STC2 complexes and the relevant biochemical and biological data reveal a wealth of information for the mechanistic interpretation of the PAPP-A’s proteolytic activity and functional involvement in placental disorders." (PMID 36550107, 2022).
polyp (1 paper, 2022). A usually exophytic mass attached to the underlying tissue by a broad base or a thin stalk. "For STC2 and CHI3L1, no significant change was observed in polyp patients in comparison with healthy controls (upper)." (PMID 35646113, 2022).
premature ovarian failure (1 paper, 2024). "NEAT1 is downregulated in premature ovarian failure (POF) mice, where it modulates the STC2/MAPK pathway to reduce apoptosis and autophagy." (PMID 39334761, 2024).
pulmonary fibrosis (1 paper, 2023). Chronic progressive interstitial lung disorder characterized by the replacement of the lung tissue by connective tissue, leading to progressive dyspnea, respiratory failure, or right heart failure. "It is still worthwhile to investigate STC2’s function in pulmonary fibrosis." (PMID 36930085, 2023). "We hypothesized that after STC2 expression was reduced, the protective effect on alveolar epithelial cells was lost, and alveolar epithelial cells were over-repaired after repeated injury and converted to fibroblasts, which finally led to the formation of pulmonary fibrosis." (PMID 36930085, 2023).
serous ovarian cancer (1 paper, 2021). "Note that STC2 was found over-expressed and might be directly regulated by HMGA2 at the transcriptional level in high-grade serous ovarian cancer." (PMID 34475994, 2021).
soft tissue sarcoma (1 paper, 2023). A malignant neoplasm arising from muscle tissue, adipose tissue, blood vessels, fibrous tissue, or other supportive tissues excluding the bones. "In soft tissue sarcoma, a signature consisting of SECTM1 and other four immune-related genes, IFIH1, CTSG, STC2, and BIRC5, could predict prognosis and the responses to ICIs23 These evidence further enhanced the correlation of SECTM1 with anti-tumor immunity." (PMID 36818292, 2023).
steatosis (1 paper, 2020). Increased lipid within the cytoplasm of cells. "Our group also observed that cinnabarinic acid mediated upregulation of STC2 can protect against microvesicular steatosis in alcoholic liver disease model." (PMID 32296395, 2020).
testicular germ cell tumor (1 paper, 2022). A germ cell tumor arising from the testis. "However, STC2 expression levels were inversely correlated with 60 ICP genes in testicular germ cell tumors (TGCT)." (PMID 35937984, 2022).
tumor (124 papers, 2005 to 2026). "Thirteen distinct cellular subpopulations within the tumor microenvironment are identified, with STC2 and ITGA5 emerging as smoking-associated prognostic markers." (PMID 41203580, 2025). "We identified a specific subset of stanniocalcin-2 positive (STC2+) malignant cells spatially enriched within tumor regions and strongly associated with poor prognosis." (PMID 41502509, 2025). "Recent studies have shown that elevated STC2 level is associated with tumor proliferation, invasion, migration, chemotherapy resistance, and poor prognosis." (PMID 38477044, 2024). "It was reported that the overexpression of Stanniocalcin 2 (STC2) was correlated with tumor growth, invasion, metastasis, and prognosis associated with many types of cancers, including liver cancer." (PMID 38971807, 2024). "The findings indicated a positive correlation between STC2 expression and tumor mutation burden (TMB) in GBM, HNSC, KIRC, LAML, PRAD, READ, THYM, and UCEC." (PMID 38229155, 2024). "STC2 is a glycoprotein that is expressed in multiple tumor tissues, and several studies have indicated that overexpression of STC2 promotes cell proliferation and migration, and is associated with tumor growth, invasion, metastasis, and poor prognosis." (PMID 39882072, 2024). "STC2 is expressed in the tumor vasculature and, when elevated, is positively associated with vascular invasion of the tumor." (PMID 37507708, 2023). "In our risk score model, three hub genes, including PPFIA4, SERPINE1, and STC2, were all identified to be differentially expressed between normal and tumor tissues and be closely associated with the prognosis and infiltration of immune cells in CC patients." (PMID 35734431, 2022). "Regulation of STC2 expression is connected with two essential conditions, namely, hypoxia and ER (endoplasmic reticulum) stress associated with the tumor microenvironment." (PMID 35646113, 2022). "Five GRGs (ABCB6, ANKZF1, B3GAT3, KIF20A and STC2) were dysregulated in tumor samples and were independently associated with the prognosis of HCC." (PMID 35123420, 2022). "Elevated STC2 levels selectiveprotectcts HeLa cells from endoplasmic reticulum stress-induced cell death and are also associated with larger tumor formation, tumor invasion, lymph node metastasis, and poor prognostic outcomes." (PMID 36713509, 2022). "In high-grade serous cancer, STC2 expression is significantly associated with the tumor grade and histotype and indicative of unfavorable outcomes." (PMID 35646113, 2022). "The broadly expressed secreted protein stanniocalcin 2 (STC2), also implicated in tumor inflammation, is an HRG interaction partner." (PMID 36078092, 2022). "We then analyzed the mutation features of STC2 in different tumor samples of the TCGA cohorts using cBioPortal database." (PMID 36685853, 2022). "STC2 is secreted as a phosphoprotein, and dysregulation of STC2 expression is linked with tumor progression and metastasis." (PMID 35646113, 2022). "STC2 has been found to be implicated in the tumor development and progression in several malignancies and appears to be a promising marker for disease severity and patient prognosis." (PMID 34612765, 2021). "Studies have found that high expression of STC2 is associated with tumor invasion, metastasis, and poor prognosis." (PMID 33029143, 2020). "STC2 expression has been associated with two essential conditions namely hypoxia and ER stress associated with tumor microenvironment." (PMID 32296395, 2020). "The human STC2 gene has been mapped to 5q35.1, which is linked with tumor progression and metastasis." (PMID 32296395, 2020). "And the results showed that the elevated STC2 expression was closely associated with the tumor size and lymph node metastasis." (PMID 32258098, 2019). "STC2 appears to be a robust phosphoprotein implicated in the processes of tumor development and progression in several malignancies." (PMID 32258098, 2019).
tumor (continued). "Clinically, STC2 has been proposed to be a biomarker for various cancers, in association with the formation of tumor neovascularization." (PMID 29748538, 2018). "We found that overexpression of the STC2 protein in surgically-resected LSCC tissues was associated with features of tumor progression and was an independent prognostic factor for OS." (PMID 24743310, 2014). "STC2 protein expression in tumor tissues was associated with invasion into the thyroid cartilage, T-Stage, lymphatic metastasis, clinical stage, and pathological differentiation (all P<0.05)." (PMID 24743310, 2014). "Additionally, STC2 has also been implicated in promoting tumor cell invasion and metastasis while concurrently inhibiting apoptosis in numerous tumor types." (PMID 40458412, 2025). "STC2's association with immune stimulatory and inhibitory genes suggests it may influence the tumor microenvironment, potentially affecting immune surveillance and response to therapy." (PMID 40535801, 2025). "A better understanding of how STC2 regulates the adaptation of tumour cells to nutrient insufficiency and the associated oxidative stress may provide new therapeutic targets." (PMID 39107307, 2024). "A better understanding of how STC2 regulates the adaptation of tumour cells to nutrient insufficiency and associated oxidative stress may provide new therapeutic targets." (PMID 38464261, 2024). "Loss of STC2 impairs tumour growth by inducing both apoptosis and necrosis in mouse xenografts." (PMID 38464261, 2024). "Therefore, it is necessary to perform a pan-cancer analysis to reveal the role and underlying molecular mechanisms of STC2 in clinical phenotypic characteristics and tumor immune microenvironments of multiple cancers." (PMID 35937984, 2022). "Subsequently, a prognostic risk score for all tumor samples was calculated using the formula: prognostic risk score = expression level of G6PD*(0.15) + expression level of CENPA*(0.075) + expression level of STC2*(0.018) + expression level of PFKFB4*(0.053)." (PMID 35938165, 2022). "Furthermore, clinical data indicate that high STC2 expression was associated with high levels of pAKT and Snail in tumor samples from HNSCC patients with regional lymph node metastasis (P < 0.01)." (PMID 27863406, 2017). "In addition, circulating STC2 mRNA was significantly associated with more characteristics of tumor migration and invasion." (PMID 24743310, 2014). "Interestingly, the expression of STC2 is closely associated with tumor progression and metastasis." (PMID 40006048, 2025). "Furthermore, the loss of STC2 suppressed E2-stimulated tumor growth in vivo, suggesting that STC2 deficiency inhibits E2-stimulated proliferation and tumor growth by activating phosphorylated-AMP–activated protein kinase (AMPK) signaling, particularly in type I EnCa." (PMID 39186548, 2024). "However, the functions of STC2 and its underlying molecular mechanisms as a tumor activator in NPC remain unclear." (PMID 33797657, 2022). "Furthermore, our study investigated the correlation of STC2 expression between prognosis, immune cell infiltration, immune checkpoint genes (ICGs), mismatch repair genes (MMRs), tumor mutation burden (TMB), microsatellite instability (MSI), and drug sensitivity in various malignant tumors." (PMID 35937984, 2022). "ADX markedly reduced intratumoral DHT and downregulated glycolytic genes (HK2, PFK2, and LDHA) and secretory proteins expressed by the tumor, including stanniocalcin 2, potentially mediating paracrine effects in the sclerotic bone response." (PMID 42149634, 2026). "STC2 contributes to multiple aspects of tumor biology, including proliferation, invasion, and metastatic spread." (PMID 41596432, 2026). "Malignant tumor cells exhibited the highest levels of STC2 expression compared to other cell populations." (PMID 41502509, 2025). "IGLV1-44 is involved in B cell differentiation, and STC2 promotes tumor development across multiple cancers." (PMID 39857718, 2025).
tumor (continued). "In vivo, METTL3 knockdown enhanced the efficacy of 5-FU and inhibited tumor metastasis, whereas STC2 overexpression counterbalanced these benefits." (PMID 40494964, 2025). "STC2 mRNA levels were consistently higher in CRC tumor tissues than in surrounding normal tissues (p < 0.001) when four public datasets (GSE18105, GSE21510, GSE39582, and GSE87211) were analyzed." (PMID 41502509, 2025). "In high-risk patients, APOD, OLR1, STC2, and DKK1 were found to be overexpressed, with APOD showing tumor-suppressive effects in certain cancers, while OLR1, STC2, and DKK1 are known to promote tumor growth and immune suppression." (PMID 39857718, 2025). "We confirmed the tumor-specific expression of STC2 using spatial transcriptomics and single-cell resolution validation." (PMID 41502509, 2025). "This study elucidates the tumor-endothelial interactions mediated by STC2 and ITGA5 in smoking-associated LSCC, emphasizing their roles in tumor progression and vascular permeability." (PMID 41203580, 2025). "Our data revealed that tumour cells exposed to Gln-free media have elevated ROS levels, and STC2 knockdown further increases ROS levels, suggesting that STC2 plays a role in maintaining redox homoeostasis." (PMID 39107307, 2024). "Taken together, our findings indicate that STC2 serves as a key regulator of redox homeostasis that governs the survival of tumour cells during nutrient insufficiency." (PMID 38464261, 2024). "We show that STC2 induction inhibits apoptosis but attenuates tumour cell proliferation during nutrient insufficiency." (PMID 38464261, 2024). "With these data in context, our study focuses on addressing how STC2 is upregulated by nutrient insufficiency, and the biological roles of STC2 in the adaptation of tumour cells to nutrient insufficiency." (PMID 38464261, 2024). "Taken together, our findings indicate that STC2 serves as a key regulator of redox homoeostasis that governs the survival of tumour cells during nutrient insufficiency." (PMID 39107307, 2024). "STC2 is a glycoprotein expressed in a broad range of tumor cells and tissues, such as human breast, colon, stomach, esophagus, prostate, kidney, liver, bone, ovary, and lung, and its overexpression promotes cell proliferation, migration, and immune response." (PMID 39119088, 2024). "Our data revealed that tumour cells exposed to Gln-free media have elevated ROS levels, and STC2 knockdown further increases ROS levels, suggesting that STC2 plays a role in maintaining redox homeostasis." (PMID 38464261, 2024). "Biologically, STC2 is involved in many biological processes in human tumours, such as cell survival, proliferation, migration and immune escape." (PMID 39107307, 2024). "Our study further confirmed the oncogenic role of STC2 in promoting tumor cell proliferation, migration, invasion, and resistance to DDP in CC." (PMID 38477044, 2024). "STC2, a glycoprotein, is expressed in a wide range of tumor cells and tissues such as human breast, colon, stomach, esophagus, prostate, kidney, liver, bone, ovary, and lung, with its overexpression promoting cell proliferation, migration, and immune response." (PMID 39119088, 2024). "Numerous studies have also explored the intriguingly complex roles of both STC1 and STC2, identifying them as potential universal tumor biomarkers and promising therapeutic targets across various cancers, including those affecting female reproductive tissues." (PMID 39186548, 2024). "To confirm the role of STC2 induction in tumour progression in vivo, we established mouse xenografts by injecting 5 × 106 Hep3B or HeLa cells with STC2 knockdown or control shRNAs independently." (PMID 39107307, 2024). "To confirm the role of STC2 induction in tumour progression in vivo, we established mouse xenografts by injecting 5×106 Hep3B or HeLa cells transfected with STC2 knockdown or control shRNAs independently." (PMID 38464261, 2024).
tumor (continued). "Through pathologist’s metastasis analysis and statistics, we confirmed the high expression of STC2 in tumor tissues." (PMID 39119088, 2024). "STC2 is often highly expressed in HCC patients, which promotes tumor progression through the AKT pathway and is associated with poor overall and disease-specific survival." (PMID 37480570, 2023). "Three genes (DTNA, STC2, and TGFBI) were differentially expressed between HNSCC tumor tissue and normal tissue, and STC2 and TGFBI were significantly up-regulated in tumor tissue, which was consistent with the analysis results." (PMID 37964257, 2023). "A pan-cancer research found that STC2 was closely related to tumor immune microenvironment including immune cell infiltration, ICGs, MMRs, TMB, and MSI." (PMID 36998462, 2023). "STC2 (stanniocalcin 2) has been reported to participate in tumor proliferation in vitro and in vivo." (PMID 36978087, 2023). "Patients with LIHC and high STC2 expression have poor prognoses, and STC2 promotes local angiogenesis, tumor proliferation, and metastasis." (PMID 37346073, 2023). "STC2 regulates tumor cell proliferation, apoptosis, and angiogenesis and is also vital for the invasiveness and metastasis of HNSCC." (PMID 39282247, 2023). "STC2 accelerated the tumorigenesis and development of tumor cells via the EMT process by stimulating the PI3K/AKT and ERK/MEK pathways." (PMID 37580737, 2023). "The results demonstrated that STC2 expression positively correlated with most RNA methylation genes across 37 tumor types." (PMID 36685853, 2022). "The prognosis of HCC patients with high STC2 expression is poor, and STC2 can promote the formation of local blood vessels, tumor proliferation, and metastasis." (PMID 36353638, 2022). "In our study, it was found that the expression of STC2 in most tumor tissues was significantly higher than that in adjacent normal tissues, except for KIRP, was lower in cancer versus adjacent normal tissues." (PMID 36685853, 2022). "STC2 as a glycoprotein is expressed in the broad-spectrum of human tumor cells and tissues, including breast, bone, esophagus, liver, lung, kidney, ovary, prostate, and stomach." (PMID 35937984, 2022). "STC2 is a glycoprotein hormone that promotes tumor development and invasion in several human malignancies." (PMID 35935989, 2022). "Currently, our laboratory is working on the detailed molecular mechanisms of how STC2 is induced upon glutamine-deprivation and its biological functions in metabolic reprogramming during tumorigenesis and tumour progression." (PMID 35501821, 2022). "For tumor purity, STC2 expression positively correlated with five types of cancers and negatively correlated with nine types of cancers, like TGCT (R = 0.44, p < 0.01) and KIRP (R = −0.22, p < 0.001)." (PMID 36685853, 2022). "In brief, elevated STC2 levels are correlated with tumour progression, disease stage and patients’ prognosis." (PMID 35501821, 2022). "Apart from its cytoprotective role under stress conditions, STC2 is correlated with tumor invasion, metastasis, and size." (PMID 35646113, 2022). "qPCR results showed that Pappa, Igf1 and Stc1 were only expressed in the CAFs, while Igf1r, Stc2 and Igfbp4 were expressed in both tumor cells and CAFs." (PMID 35205651, 2022). "Stanniocalcin 2 over-expression is detected in various human cancers where it helps tumor cells to adapt to the stressful conditions in tumor microenvir-onment with hypoxia and glucose deprivation, thus increasing tumor ability to invade and progress." (PMID 35096084, 2022). "Current evidence suggests that the activation of STC2 gene expression usually occurs in hypoxia, which is a common feature in the tumor microenvironment." (PMID 35102149, 2022). "STC2 regulates various aspects of tumour biology like cell proliferation, invasion and metastasis that are associated with tumour phenotypes and disease stages." (PMID 35501821, 2022).